CTXND2 (cortexin domain containing 2)
Gene: Protein-coding gene on chromosome 1 (150,887,136 to 150,913,292, forward strand). Ensembl gene ENSG00000283324.
Subcellular location: Membrane
Gene Ontology:
Cellular component: membrane
Homologues: Orthologues: chimpanzee CTXND2 (98% identical), dog CTXND2 (93% identical), pig CTXND2 (91% identical), rabbit CTXND2 (89% identical), mouse Ctxnd2 (75% identical).